CXCR4 (C-X-C motif chemokine receptor 4)
Diseases named in the same sentence as CXCR4 in open-access papers (continued):
Sharing a sentence is not in itself a finding about the gene and the disease.
breast carcinoma (continued). "CXCL12 functions through CXCR4 on endothelial cells to significantly enhance adhesion of circulating breast cancer cells, independent of CXCR4 or CXCR7 on cancer cells." (PMID 19484126, 2009). "In the present study, treatment of the MDA-MB-231 breast cancer cell line, which express Nrp2, endogenous VEGF-C, and cytoplasmic or nuclear CXCR4, with anti-Nrp2 antibody significantly inhibited cytoplasmic CXCR4 protein expression." (PMID 19580679, 2009). "When added from the basal side, CXCL12 acts through receptor CXCR4 on endothelium to promote adhesion of circulating breast cancer cells, independent of CXCL12 receptors CXCR4 or CXCR7 on tumor cells." (PMID 19484126, 2009). "However, except for CXCR4/CXCL12, little is known about the relation between tumour-related chemokine expression and the development and progression of solid tumours like breast cancer." (PMID 18781150, 2008). "The NO donor DETA NONOate induced cytoplasmic expression of functional CXCR4 protein expression in breast cancer cell lines." (PMID 19025611, 2008). "While CXCR4 and another chemokine receptor, CCR7, are highly expressed on the surface of human breast cancer cells, CXCL12 and a CCR7 ligand, CCL21, are highly expressed in lymph nodes, bone marrow, lung and liver, which form the common metastatic destinations of breast cancer." (PMID 19787093, 2008). "Recently, for breast cancer, it was shown that only cytoplasmic staining of CXCR4 had significant impact on prognosis, but not nuclear staining – using the same antibody as we used for our study." (PMID 17245339, 2007). "Therefore, our results are in line with recent publications from our group and others, reporting a similar effect of CXCR4 on disease dissemination in other tumour entities, such as non-small-cell lung cancer (NSCLC), colorectal or breast cancer." (PMID 16819541, 2006). "In this regard, the expression pattern of the luciferase protein, the product of the luciferase gene in the recombinant Ad vector driven by the CXCR4 promoter and the CMV promoter, was determined in breast cancer tissue slices and normal breast tissue slices using immunofluorescent detection." (PMID 16457694, 2005). "In this regard, candidate breast cancer TSPs include promoters of the genes for the epithelial glycoprotein 2 (EGP-2), cyclooxygenase-2 (Cox-2), α-chemokine SDF-1 receptor (stromal-cell-derived factor, CXCR4), secretory leukoprotease inhibitor (SLPI) and survivin." (PMID 16457694, 2005). "However, despite the accumulated information on CXCR4, few studies have been conducted to evaluate SDF-1 expression and its prognostic value in patients with breast cancer." (PMID 15987445, 2005). "Future research should further explore the potential of CXCR4-targeted PET imaging in selecting patients with triple-negative breast cancer and high-grade breast cancer who may benefit from CXCR4-targeted therapies and monitoring response to therapy, particularly in the context of HIV co-infection." (PMID 40075611, 2025). "Interestingly, bioinformatic analysis on CXCR4 expression in breast cancer using TNM plot database revealed that CXCR4 was upregulated in breast cancer samples as compared to normal breast tissues (p = 3.77e-22)." (PMID 40548301, 2025). "Future research should further explore the potential of CXCR4-targeted PET imaging in selecting patients with triple-negative breast cancer and high-grade breast cancer who may benefit from CXCR4-targeted therapies, particularly in the context of HIV co-infection." (PMID 40075611, 2025). "Furthermore, CB activation could interfere with breast cancer bone metastasis via C-X-C motif chemokine ligand 12 (CXCL12) and C-X-C motif chemokine receptor 4 (CXCR4) pathway." (PMID 39527598, 2024).
breast carcinoma (continued). "For instance, an Anti-CXCR4- targeted liposome encapsulating LCN2 siRNA effectively targets metastatic breast cancer cells and significantly blocks migration in triple-negative human breast cancer cells (88% for MDA-MB-436 and 92% for MDA-MB-231) along the CXCR4-CXCL12 axis." (PMID 39188682, 2024). "Notably, CXCR4 has been identified as the therapeutic target of Balixafortide, whereas AKT1 as the therapeutic target of Capivasertib and Ipatasertib, all of which have been subjected to rigorous scrutiny in phase III clinical trials for breast cancer." (PMID 38887235, 2024). "Given the role of the CXCR4/CXCL12 axis in breast cancer metastatic spread, and the differences observed between MDA-MB-231 and MCF-7 cells, our data point to initial stages of breast cancer as possible models where targeting the CXCL12/HMGB1 heterocomplex could be particularly promising." (PMID 38803493, 2024). "Moreover, CXCR4’s involvement in drug resistance, particularly in trastuzumab treatment, has been well documented, reinforcing its critical role in the therapeutic landscape of HER2 breast cancer." (PMID 39682150, 2024). "The relationship of the expression levels of SDF-1 and CXCR4 with the clinicopathological features of severe preeclampsia was analyzed, and Spearman correlation of the relative expression levels of SDF-1 and CXCR4 with different epithelial breast cancer stages was carried out." (PMID 35545781, 2022). "Differential gene expression analysis between breast cancer patients (n = 2509) with high and low GIT1 levels revealed significantly increased expression of aldehyde dehydrogenase 1 (ALDH1) and C-X-C chemokine receptor type 4 (CXCR4) in the patients with low GIT1." (PMID 35318302, 2022). "CXC-chemokine receptor 4 (CXCR4) is the only known CXCL12 receptor, and the biological axis system formed by the two plays an important role in targeted metastasis of various malignancies including breast cancer, prostate cancer, hepatocellular carcinoma, and neuroblastoma." (PMID 35463082, 2022). "In breast cancer, some reports suggest that both receptors are found in the same cell, whereas others report that CXCR4 and ACKR3 are found in distinct cell subsets, with uptake of CXCL12 by ACKR3+ BC cells enhancing proliferation and metastatic potential of CXCR4+ cells." (PMID 36233192, 2022). "In addition, GST-NT21MP, which is a synthetic 21-mer peptide antagonist of CXCR4 (NT21MP) derived from the viral macrophage inflammatory protein II, was found to block the CXCR4 pathway, thus decreasing SDF-1-induced cell growth, adhesion and migration capacities in breast cancer cell lines." (PMID 36140541, 2022). "However, a possible physical association between CXCR4 and CCR7 or its functional significance in relation to breast cancer progression has not been previously investigated." (PMID 34685420, 2021). "However, counteracting neutrophil trafficking (by NLRP3 inhibition) or neutrophil aging (by CXCR2 blockade) attenuated tumor progression, whereas supporting neutrophil aging (by blockade of CXCR4) even enhanced tumor growth in SCC VII HNSCC and 4T1 breast cancer." (PMID 34876407, 2021). "There are several CXCR4 inhibitors under clinical trials for the treatment of multiple myeloma, small cell lung cancer, and leukemia, although none has been reported for breast cancer." (PMID 33986665, 2021). "Moreover, besides its involvement in breast cancer cell stemness by modulating glycolytic gene expression, we show that ETV4 also activates SHH signaling to promote breast cancer stemness via transcriptionally regulating its target gene CXCR4." (PMID 34052833, 2021). "However, the expression of CXCR4 is low or non-existent in normal breast tissue but relatively high in breast cancer cells." (PMID 33919589, 2021).
breast carcinoma (continued). "Previous research has been reported that miR-130b-3p present in exosomes contributes to CXCL12/CXCR4-induced colorectal cancer metastasis into liver and downregulate PIEZO2, thereby activating the Hedgehog signaling pathway and leading to worsening breast cancer prognosis." (PMID 33612479, 2021). "In an orthotopic immunocompromised breast cancer model, overexpression of syndecan‐2 in TASCs significantly enhanced TGFβ signalling (SMAD7, PAI‐1), tumour growth and metastasis, whereas reducing levels of SDC2 in TASCs attenuated TGFβ signalling (SMAD7, PAI‐1, CXCR4), tumour growth and metastasis." (PMID 33152121, 2021). "Very recently it has been shown that CXCR4 inhibitor AMD3100 decreased desmoplasia, immunosuppression and increased T cells infiltration into tumors, and thereby enhanced the efficacy of immune checkpoint inhibition in a pre-clinical murine model of breast cancer." (PMID 33414786, 2020). "Interestingly, it has been reported that ligand-activated PPARγ can inhibit CAF-induced effects on breast cancer cell interfering with the CXCR4/stromal cell-derived factor-1 (SDF-1) α axis, which plays a crucial role in mediating breast cancer cell invasion and metastasis." (PMID 33352766, 2020). "However, whether the CXCL12/CXCR4 and the HFG/c-MET axis hold similar significance in male breast cancer is unknown." (PMID 32188473, 2020). "Utilizing the ability of ExoCXCR4+TRAIL to cross the BBB and its advantages of being an excellent gene vector, we investigated whether a combination of CXCR4, TRAIL, and carboplatin used in the clinic was effective to treat a brain metastasis of breast cancer model." (PMID 32850457, 2020). "Recently, the anti-neoplastic agent Balixafortide (a potent and selective CXCR4 antagonist) (Polyphor) in combination with Eribulin (non-taxane, anti-microtubule drug) has been successfully employed in stage IV breast cancer in a phase Ib/proof of concept clinical trial (NCT01837095)." (PMID 31681564, 2019). "In addition, in breast cancer, it downregulates the expression of VEGFR1 and CXCR4." (PMID 30871059, 2019). "Breast cancer cell studies showed that butein inhibits ER+ MCF-7 cells growth, and blocks CXCL12-induced migration and invasion of human epidermal growth factor receptor 2 positive (HER2+) in SKBR-3 breast cancer cells by repressing NFқB-dependent CXCR4 expression." (PMID 31665136, 2019). "None of the compounds were toxic to lymphocyte, monocyte or macrophage cells, suggesting that aggressive breast cancer carcinomas may be selectively targeted and eliminated using CXCR4-based therapies without additional cytotoxic agents." (PMID 29682200, 2018). "The purpose of this study was to investigate whether NRF1-modulated CXCR4 expression drives estrogen-induced malignant transformation of breast epithelial cells to BCSCs and whether this NRF1 activity plays a major role in breast cancer development and progression." (PMID 30486409, 2018). "The interaction between chemokine receptor type 4 (CXCR4) and its cognate ligand stromal-derived factor-1 (SDF1 or CXCL12) plays a crucial role in the regulation of migration and metastasis in a variety of solid tumors including breast cancer (Balkwill, 2004a,b)." (PMID 30564115, 2018). "Our discovery of targeting transcriptional activation of CXCR4 to inhibit NRF1-induced oncogenic transformation provides a mechanistic explanation for estrogen-dependent breast carcinogenesis and opens new avenues in strategic therapeutics to fight breast cancer." (PMID 30486409, 2018). "CXCR4 and CXCL12 expression was analyzed by immunohistochemistry and immunofluorescence on primary tumors (PT), regional and distant metastases of female cats with mammary carcinoma and correlated with serum CXCL12 levels, tumor molecular subtypes and clinicopathological features." (PMID 30012106, 2018).
breast carcinoma (continued). "ALX40-4C (N-α-acetyl-nona-d-arginine amide acetate), which selectively blocks the interaction of SDF-1 with CXCR4, inhibits breast carcinoma cell invasion without decreasing cell viability, suggesting a distinct contribution of CXCR4 to the invasion but not to the survival of breast cancer cells." (PMID 30513833, 2018). "Consequently, based on this pilot study with a small patient cohort, CXCR4-targeted PET failed to clearly demonstrate its usefulness for imaging of breast cancer." (PMID 30191351, 2018). "Moreover, cats with CXCR4 positive PT exhibited significantly lower serum CXCL12 levels than cats with CXCR4 negative mammary carcinomas (p = 0.0324)." (PMID 30012106, 2018). "Furthermore, a CXCR4 antagonist (AMD3100) prevents macrophage accumulation and delays tumor relapse after cyclophosphamide treatment in subcutaneously transplanted lung cancer and in orthotopic mammary cancers." (PMID 30483271, 2018). "We used a breast cancer cell line that does not express CXCR4 to determine whether NT21MP inhibits the EMT process through the CXCR4/PDGFRα signaling pathway and demonstrated that NT21MP targeted CXCR4, inhibits EMT, and inhibits tumor progression." (PMID 28415580, 2017). "NCOA1 has previously been reported to be overexpressed in breast cancer and its increased expression positively correlated with disease recurrence and metastasis through working with multiple transcription factors to, in turn, upregulate the expression of Twist1, ITGA5, CSF-1, SDF1 and CXCR4." (PMID 28060733, 2017). "In vitro, the effects of NT21MP, CXCR4 and PDGFRα on tumor EMT were assessed by relative quantitative real-time reverse transcription–polymerase chain reaction, western blot and biological activity in breast cancer cell lines expressing high or low levels of CXCR4." (PMID 28415580, 2017). "Moreover, since the SDF-1/CXCR4 axis elicits the activation of multiple kinase pathways (e.g. PI3K, MAPK, ERK1/2), its inhibition may represent a new therapeutic strategy to treat mammary tumors more effectively." (PMID 29285291, 2017). "Because CXCR4 is expressed in all subtypes and to the highest degree in TNBCs, breast cancer patients who do not benefit from hormonal or anti-HER-2 therapy may potentially benefit from CXCR4 targeted therapies." (PMID 26848769, 2016). "CXCR4 antagonists, were first evaluated in the treatment of HIV, later was discovered their potential for mobilizing CD34+ hematopoietic peripheral stem cells, but these classes of drugs are promising anticancer drugs and several clinical trials are ongoing including breast cancer." (PMID 26896000, 2016). "In addition, studies in various cancer cell lines, including breast cancer cells, established key roles for P-Rex1 in cell migration stimulated by growth factors such as HRG as well as GPCR ligands such as SDF-1, a chemokine that activates CXCR4." (PMID 27351228, 2016). "Estrogen also promotes the epithelial-mesenchymal transition and stemness of ER-positive breast cancer cells through hedgehog signaling activation, G protein-coupled estrogen receptor (GPCER) regulation, or crosstalk to Notch signaling, SDF-1/CXCR4 signaling and TGFβ signaling." (PMID 26845172, 2016). "The CXCR4-SDF-1 interaction may lead to actin polymerization and pseudopod formation, thereby resulting in chemotaxis and invasion, while the specific blockade of CXCR4 inhibits the metastasis of breast cancer cells to lymph nodes and bone marrow." (PMID 25846512, 2015). "In addition to having a higher affinity for the migration surface and CXCR4, CXCL12-γ is present at lower levels within the tumor environment, and lower levels of CXCL12 correlate with increased metastasis in mouse models and worse prognosis in breast cancer." (PMID 25909600, 2015). "However, the exact mechanisms of how CXCR4 and CXCL12 enhance metastasis and/or tumor growth and their full implications on breast cancer progression are unknown." (PMID 24810923, 2014).
breast carcinoma (continued). "A number of functional studies investigating the influence of CXCR4 expression and activation by its ligand CXCL12 have recently been performed, revealing that CXCR4-CXCL12 axis plays an important role in regulating metastasis of breast cancer to specific organs." (PMID 24810923, 2014). "Importantly, CXCR4 mRNA was higher in stem cell-enriched CD44+ /CD24− - patient-derived breast cancer cells compared to non-enriched cells." (PMID 24583601, 2014). "However, in luminal or HER2-positive breast cancer groups, CXCR4 was not correlated with such clinic-pathological characteristics and survival." (PMID 24591761, 2014). "However, several markers, including CD133, CD24, CD44, CD166, EpCAM (CD326), CXCR4 (CD184), c-kit (CD117), and among others have been identified as surface markers of CSCs isolated from glioblastoma, breast cancer, pancreatic cancer, prostate cancer, or hepatocellular carcinoma." (PMID 24675390, 2014). "In breast cancer, PDGF-D could activate CXCR4 to promote lymphatic metastasis." (PMID 24646915, 2014). "However, in contrast to breast cancer cells, Slit2N did not have any effect on the downregulation of either CXCR4/CCR5 or CD4 expression, ruling out down-modulation of HIV-1 receptors/co-receptors as a mechanism of action for Slit2." (PMID 23294842, 2013). "Increasing evidence shows that CXCR4 and its ligand stromal-derived factor-1 (SDF-1α, also known as CXCL12) may play a critical role in the organ-selective process of tumorigenesis and metastasis including those observed in breast cancers." (PMID 23484027, 2013). "This was not the case in HER2-positive breast cancer patients, suggesting that receptor CXCR4 may be used to distinguish between patients with long- and short-term survival." (PMID 24649267, 2013). "Recently, Altenburg and Siddiqui found that treatment of the aggressive MDBA-MB-231 breast cancer cells with ω-3 PUFAs resulted in reduced surface but not overall C-X-C chemokine receptor type 4 (CXCR4) expression and subsequently in reduced CXCR4-mediated cell migration." (PMID 23762838, 2013). "In breast cancer cells, a similar functional relationship between the PDGFR pathway and CXCR4 has been reported, whereby overexpression of PDGF-D, which specifically binds to and activates PDGFRB, was shown to induce CXCR4 expression and promote lymph node metastasis." (PMID 23497290, 2013). "Taken together, CXCR4 and CXCL12 may indeed play critical roles in breast cancer metastasis." (PMID 22485156, 2012). "Beside CXCR4 expression, a phenotypic characterization of the cells from the primary cultures was performed, by analyzing the expression of common mammary lineage markers (CK14, CK18, EMA, ER-α), or proteins (EGFR and HER-2/neu) overexpressed in mammary carcinoma conferring malignant behaviour." (PMID 22417013, 2012). "Not all breast cancer patients respond in the same manner to chemotherapy, and the down-regulated expressions of CXCR4 and C-erbB-2 after primary chemotherapy may be a sensitive response to treatment." (PMID 23046610, 2012). "SDF-1α and its specific receptor CXCR4, which expressed on the membrane of tumor cells, form the SDF-1α/CXCR4 chemokine axis and play a pivotal role in migration, invasion and metastasis of some malignant tumors, such as melanoma, breast cancer and non-small cell lung cancer cells." (PMID 23300882, 2012). "In another study, higher expression of CXCR4 mRNA in metastatic cells as compared with cells from primary tumours was reported, altogether with the observation that neoplastic cells from feline mammary carcinomas express more CXCR4 than non-neoplastic mammary tissues." (PMID 22417013, 2012). "In the setting of profound hypoxia and CXCR4 up-regulation in Treg, as occurs in basal-like breast cancer, CXCL12 may have a negative consequence of enhancing Treg recruitment and suppressing the anti-tumour immune response." (PMID 21521526, 2011).